CD4 (CD4 molecule)
Diseases named in the same sentence as CD4 in open-access papers (continued):
Sharing a sentence is not in itself a finding about the gene and the disease.
tumor (continued). "Patients without MVI, those with intact tumor capsules, and those exhibiting high CD4+ T cell density in central tumor regions demonstrated significantly prolonged RFS." (PMID 41212769, 2025). "Consistently, ssGSEA showed higher activity or abundance of immature dendritic cells (iDCs), Mφ, MHC class I, CD4+ T helper cells, and tumor-infiltrating lymphocytes (TILs)in the HRG than in LRG." (PMID 41019083, 2025). "T cells, particularly CD8+ and CD4+ subsets, mediate direct anti-tumor responses, while B cells support immunity through antigen presentation, antibody production, and TLS formation." (PMID 41008839, 2025). "Mechanistically, Tregs promote osteosarcoma cell proliferation primarily by suppressing tumor‐eliminating immune subsets, including CD4+ and CD8+ T cells as well as monocytes." (PMID 41357670, 2025). "Tumor‐secreted TGF‐β drives differentiation of CD4+ T cells into Treg cells, which exhibit enhanced glucose uptake and glycolysis capacity, further intensifying glucose scarcity." (PMID 41427020, 2025). "T cells play a pivotal role in the tumor microenvironment; CD8+ cytotoxic T cells are responsible for recognizing and eliminating tumor cells, while CD4+ helper T cells modulate the functions of other immune cells through cytokine secretion." (PMID 40270890, 2025). "In GD, GlcCer accumulation due to lysosomal β-glucocerebrosidase deficiency results in the persistent expression of tumor-associated macrophage markers (e.g., CD163), CD206-positive bone marrow mesenchymal stromal cells, and activated CD4+T cells." (PMID 41155172, 2025). "Murine tumor models have revealed detailed mechanisms of B cell mediated CD4 and CD8 T cell activation." (PMID 40356924, 2025). "We next decided to use mice with the tamoxifen-inducible CD4+ T-cell-specific deletion of Bcl-6 (Bcl6fl/flCD4CreER) to define the impact of Bcl-6 deletion on the early and late stage of anti-tumor CD4+ T-cell response to M002 treatment." (PMID 39885128, 2025). "This extract appears to have minimal toxic effects on liver and kidney functions in tumor-bearing mice and enhances the immune response by increasing white blood cell and lymphocyte counts, including natural killer cells and T-cells (CD4+ and CD8+ cells)." (PMID 40141325, 2025). "This tumor development was prevented when CD4+, CD25+, FOXP3+ Tregs were depleted, indicating that T. muris infection influences CRC through immunosuppression mediated by Tregs." (PMID 41011849, 2025). "These insights will aid in understanding the diversity and functionality of antitumor CD4+ T cell responses and should allow the development of strategies through which these can be therapeutically manipulated to favor tumor control." (PMID 40196575, 2025). "This suggests a correlation between the peripheral immune response and the cellular dynamics within the tumor, supporting the notion that CD4+ T cells are integral to the mechanism of action of the gM-enhanced cancer vaccine." (PMID 40426190, 2025). "CIBERSORT analysis identified enrichment of TFH and CD4 T‐cell memory (activated), while B‐cells and dendritic cells progressively decreased, indicating selection of tumor T‐cell clones that were less TME‐dependent." (PMID 40510016, 2025). "In the immunosuppressive TIME, tumor-specific antigens and the influence of inhibitory cytokines lead to apoptosis of inactivated CD4+ and CD8+ T cells and cytotoxic T lymphocytes, a process that curcumin has been shown to reverse effectively." (PMID 40940890, 2025). "A visual representation of the infiltration patterns of 22 immune cells revealed increased levels of activated mast cells, neutrophils, resting natural killer cells, M0 macrophages, M1 macrophages, and activated CD4 memory T cells in tumor samples." (PMID 39963131, 2025). "This chemokine is secreted by CD4+ T cells and guides B cells toward the tumor site, facilitating the assembly of TLSs." (PMID 40534852, 2025).
tumor (continued). "B lymphoblastoid cell-derived EVs carry FASL molecules, which cause CD4+ T cells to undergo apoptosis through FAS and FASL, to diminish the anti-tumor response." (PMID 41551601, 2025). "While cytotoxic T lymphocytes are central to the anti-tumor immune response, both B cells and CD4+ T helper cells are essential for antigen recognition and the orchestration of adaptive immunity." (PMID 41019053, 2025). "A possible explanation was that HAIC‐induced release of tumor antigens was processed and presented by cDCs and B cells to elicit antigen‐specific T cell response, promoting naïve CD4+ T cells differentiation into TFH cells and T helper cells." (PMID 39686623, 2025). "Cellular immunity, mediated by tumor antigen-specific CD4+ and CD8+ T cells, has a critical role in the success of cancer immunotherapy by targeting intracellular driver and passenger tumor mutations." (PMID 40790272, 2025). "Tumor-infiltrating lymphocytes (TILs), a genetically diverse population of immune cells associated with TME, including CD8+ T lymphocytes and CD4+ T1 lymphocytes, have been linked with favorable outcomes." (PMID 39958358, 2025). "Tregs are the most prominent immunosuppressive cells in the tumor microenvironment, and accumulating evidence suggests that their heterogeneity contributes to distinct suppression mechanisms on CD4 T cells." (PMID 40959273, 2025). "The interactions of cDCs with NK and CD4+ T cells have been shown to be critical for the establishment of anti‐tumour immune responses." (PMID 40878038, 2025). "The cytotoxic CD4+T lymphocyte subpopulation recognizes the Hsp70 molecule on tumor cells using Tag7 on its surface and also kills them through FasL-Fas interaction." (PMID 40362307, 2025). "infection led to an increase in IL-17A+ CD4+ T cells and γδ T cells, both involved in chronic inflammation and tumour progression." (PMID 40278081, 2025). "Efficient tumor cell killing was maintained with either CD4+ (Ad‐CIITA: 75.6% ± 16.8) or CD8+ T‐cells (Ad‐CIITA: 67.5% ± 28.8)." (PMID 39535369, 2025). "Immune-inflamed tumors feature dense CD8+/CD4+ T cell infiltration and PD-1/PD-L1 activation near tumor nests, correlating with better responses to ICIs." (PMID 40510347, 2025). "CD5 expression was significantly reduced in malignant CD4 T cells from tumor-stage MF lesions compared to patch/plaque MF lesions." (PMID 41226451, 2025). "In primary tumor tissue, infiltrating CD4+ T cells negatively correlated with Apo-A1 protein level and arginase-1 expression in infiltrating neutrophils." (PMID 40358184, 2025). "Compared to untreated tumours, CD4+ T cells in sensitive tumours express higher levels of PD‐1, while CD8+ T cells in imatinib‐resistant tumours also exhibit elevated PD‐1 expression." (PMID 41230918, 2025). "The CD4+ T cell ratio, by normalizing these counts, provides a more stable and reliable measure of immune function, particularly in the context of tumor immunity." (PMID 41179889, 2025). "When combined, the enhanced expression of MHC class II molecules induced by HDACi improves the efficiency of tumor antigen presentation, activating more CD4+ T cells." (PMID 40573881, 2025). "Non-responders and partial responders showed an immune excluded TME, characterized by substantial whole-tumor CD4+ T cell presence and limited CD8+ T cells at the tumor periphery with little to no inner tumor presence." (PMID 41041061, 2025). "The death of tumor cells, along with the release of tumor antigens, then lead to the further spread of antigens which stimulate the release of further CD4+ and CD8+ T cells." (PMID 40061134, 2025). "Depletion of Treg cells led to augmentation of the OVA-specific antitumor immune response involving activation of TRM-like CD8+ TILs, substantial CD8+ and CD4+ T cell infiltration, and a decrease in tumor growth." (PMID 41279375, 2025).
tumor (continued). "Lastly, PD1 expression on T-cells, measured by the PD1/CD4 ratio, was significantly higher in cases with tumor spread through air spaces (STAS) (p = 0.010), with values of 0.90 ± 0.17 in cases with STAS and 0.73 ± 0.41 in cases without STAS." (PMID 41375087, 2025). "The classical paradigm held that tumor-specific immune responses required DC migration from primary tumors to SLOs, where naïve CD4+ T cell activation occurred following tumor antigen presentation." (PMID 40475020, 2025). "In this study, we found that lidocaine treated-CD4+CD25+ TIICs had anti-tumor immunity by decreasing suppressive IL-35 cytokine expression." (PMID 40244064, 2025). "Our results identify an intricate interplay between the Fc effector function of anti-CTLA-4 antibodies, IFNγ-producing effector CD4+ T cells, and tumor endothelial cells." (PMID 40460830, 2025). "Mice were treated with isotype control or anti-CD4 antibody to deplete CD4+ T cells before and after tumor re-challenge." (PMID 39885128, 2025). "The proportion of CD8+T cell was increased in tumor tissue, but the proportion of CD4+T was decreased." (PMID 41438767, 2025). "These vaccines enhance antigen presentation, which activates CTLs and CD4+ T cells, leading to a potent anti-tumor response." (PMID 40497988, 2025). "Platelets dual-labeled with iron oxide nanoparticles (for photothermal therapy) and anti-PD-L1 antibodies achieved synergistic tumor control and enhanced CD4+ and CD8+ T-cell infiltration following surgical removal of residual disease." (PMID 40514754, 2025). "This procedure alters the (generally) poor tumor immunogenicity into highly immunogenic material and creates neoepitopes that can be presented by DC to both CD4+ and CD8+ T cells and thereby break immune tolerance." (PMID 41374974, 2025). "Ligand‒receptor analysis revealed that azvudine predominantly regulated signal transduction from tumor CD4+ T cells to other immune cells through SPP1-(ITGAV + ITGB5) and SPP1-(ITGAV + ITGB1), as well as COL1A1-(ITGA9 + ITGB1), COL1A1-CD44, and COL1A1-SDC4." (PMID 39819859, 2025). "In the subset of patients with an increase in the percentage of CD38+ lymphocytes in response to modakafusp alfa, there were also increases in CD8+ and CD4+ T-cell activation (%CD69) as well as CD8+ T-cell cytotoxic function (%GzB) in the tumor biopsies." (PMID 41445795, 2025). "Strikingly, we found that the triple combination led to increased MHC-II on tumor cells 7 days after treatment initiation, indicative of possible direct cross-talk between residual tumor cells and CD4 T cells." (PMID 40299790, 2025). "At a later stage of tumor growth, combining our DC vaccine with Treg depletion directly or through CD4+ T cell depletion further enhanced tumor suppression." (PMID 40857404, 2025). "CD3+CD4+ splenocytes isolated from young 4T1 tumor-bearing mice were differentiated into Th17 lymphocytes." (PMID 40894304, 2025). "The high-PCD group exhibited an increased proportion of terminally exhausted CD4+ T cells, indicating a state of immune exhaustion that compromises anti-tumor immunity." (PMID 40740783, 2025). "CD8 + T cells exert direct anti-tumor effects through cytotoxicity, whereas CD4 + T cells, as central mediators of both innate and adaptive immunity, also contribute to anti-tumor responses." (PMID 41225436, 2025). "Due to the important role of CD8 + T cells in anti-tumor immunity and the low abundance of CD4 + T cells in our dataset, our analysis focused primarily on the CD8 + T cell compartment." (PMID 40973768, 2025). "The tumor-specific CD4+CTLs exert antitumor action that can be leveraged to increase the efficacy of other available cancer immunotherapies." (PMID 41009359, 2025). "In HIV-infected individuals, where the immune system is compromised, maintaining a higher CD4+ T cell ratio is particularly important for effective immune surveillance and tumor control." (PMID 41179889, 2025).
tumor (continued). "To test this idea, we treated CD4+ T cells with tumor tissue supernatant during their in vitro activation, and found that cleavage of GSDMD and of caspase-8 were both weakened, leading to reduced production of IL-2." (PMID 40759573, 2025). "The 73 − 10 positivity was evaluated using a tumor cell score ≥ 1%, and the results were analyzed against clinicopathological features including CD4+ and CD8+ tumor-infiltrating lymphocytes (TILs), and clinical outcomes." (PMID 40392349, 2025). "Why CD4+T cells and cDC1 are specifically attracted to 4T-1 tumor remains elusive, and chemokine level changes following the treatment of F1/F3 will be the focus of our upcoming study." (PMID 40573908, 2025). "FOXP3, a canonical marker of regulatory T cells (Tregs), was significantly upregulated in CD4+ T cells from tumor tissues compared to adjacent controls (1.100 vs. 0.469, P < 0.05), indicating an accumulation of immunosuppressive Tregs within the TME." (PMID 41181122, 2025). "This included an increase in tumor-infiltrating lymphocytes and a rise in splenic CD4+ cells, thereby boosting the immune response against the tumor." (PMID 40005517, 2025). "Collectively, these findings indicate that specific subsets of CD4+ T cells help create a sanctuary in the bone marrow that protects tumor cells from immune attack." (PMID 40902549, 2025). "In this setting, CD4+ T cell depletion suppressed tumor growth even under NK cell-depleted conditions." (PMID 40558520, 2025). "TIM-1 can target and inhibit B cells, enhance anti-tumor CD8+ and CD4+T cell responses, and inhibit tumor growth, which is of great significance for cancer treatment." (PMID 40356928, 2025). "CD4+ Treg lymphocyte subsets, often present in the tumor, promote EMT by secreting IL-10 and TGF-β, which activate signaling pathways supporting the loss of epithelial features and acquisition of a mesenchymal phenotype by tumor cells." (PMID 40362280, 2025). "Significant alterations in cell populations were observed following RBΔCDK activation; tumor cell and neutrophil populations declined, while B and T cell populations increased, along with upregulation of Cd4 and Cd8 in the T cell cluster." (PMID 41326426, 2025). "Module 2 featured correlations among CD8 FTL+ Tex cells, CD4 Treg cells, plasma B cells, and two tumor meta-programs (MYC and unfolded protein response)." (PMID 40890106, 2025). "As a major immune component of the tumor microenvironment, the response of CD4+ T cells serves as an indicator of the host immune reaction to tumor cells." (PMID 41184982, 2025). "A study discovered that N1 TANs can activate peripheral blood CD4+ T cells by binding their Fc receptors to IgG Fc receptor proteins on tumor cells, leading to tumor cell destruction and reduced tumor growth." (PMID 40387965, 2025). "CD4+ T cells can be targeted to tumor cells in a variety of ways, by both direct cytolytic mechanisms and indirectly by regulating the tumor microenvironment." (PMID 41230345, 2025). "The abundance of tumor-infiltrating CD4+ T cells was increased by 3–12-fold over the saline control in the GSC005 tumor and peaked around day 14 post-M002 treatment in both GBM models." (PMID 39885128, 2025). "The HMP1G NPs group exhibited a significant CD8+ T cell infiltration in the tumor bed, along with an increase in GrzB levels, and a decrease in the number of CD4+ T cells and the level of Foxp3." (PMID 39661740, 2025). "The primary endpoint of the trial was the evaluation of the changes in the CD4/CD8 ratio in the tumor microenvironment." (PMID 41097726, 2025). "The authors concluded that upregulation of epidermal TSLP can generate anti-tumor CD4+ T cell response in a Th2 inflammatory microenvironment." (PMID 40873585, 2025). "Current research is focused on CD4+ T cell function in tumor immune evasion and anti-tumor immunity." (PMID 40422244, 2025).
tumor (continued). "Mechanistically, Akkermansia induced IL-12 production, which promoted the infiltration of CCR9+CXCR3+CD4+ T lymphocytes into the tumor microenvironment, thereby rescuing ICI responsiveness." (PMID 41030553, 2025). "The immunosuppressive cytokines and checkpoints in the GBM TME derive not only from tumor cells, but also from TAMs and regulatory T cells (Tregs), the suppressive subset of CD4+ T cells." (PMID 41583439, 2025). "These Tregs suppress the activity of effector T cells, such as CD8+ cytotoxic T-lymphocytes (CTLs) and CD4+ helper T cells, reducing their ability to mount effective immune responses against tumor cells." (PMID 40281554, 2025). "Our data suggest an important contribution of Tbet+ICOS+ Th1-like CD4+ T cells in the remodeling of tumor blood vessels and the increase of TA-HEVs during treatment with anti-CTLA-4 antibodies." (PMID 40460830, 2025). "We found that YFD treatment resulted in a substantial increase in CD4+ and CD8+ T cells, a reduction in myeloid-derived suppressor cells (MDSCs) and tumor-associated macrophages (TAMs), and an increase in the M1/M2 ratio of TAMs in tumors." (PMID 41098716, 2025). "NSG-Quad and MISTRG-6 mice displayed a higher frequency of tumor-infiltrating myeloid cells compared to NSG mice, whereas NSG-Quad and MISTRG-6 mice had less tumor-infiltrating CD4+ T cells compared to NSG mice." (PMID 40503011, 2025). "PADI2 is capable of citrullinating the nuclear antigen Nucleophosmin at position 277, a modification that can be targeted by CD4 T cells for anti‐tumour therapy." (PMID 40078091, 2025). "In the MPR_Pre-NAIC_Tumor and MPR_Post-NAIC_Tumor groups, CD4+ T cells were enriched with the CXCL13 signaling pathway and T cell-induced cell death process, whereas the Tregs differentiation process was weakly enriched in the MPR_Post-NAIC_Tumor." (PMID 40295492, 2025). "In murine GBM models, initial infiltration of CD8+ and CD4+ T cells is observed during early tumor development, but as tumor cells proliferate they become immune evasive, with tumor-infiltrating T cell numbers declining markedly." (PMID 41583439, 2025). "Flow cytometry results suggested that the CD4+/CD8+ T cell ratios were also raised in non‐stressed tumour‐bearing mice compared to both controls and stressed mice with TNBC." (PMID 40172096, 2025). "The expression level of TNF was positively correlated with the infiltration abundance of CD8 + T Cell, CD4 + T Cell, Neutrophil, and Dendritic Cell, but negatively correlated with tumor purity." (PMID 41287122, 2025). "In responders, 64Cu-CD4-Nb1 predominantly accumulated in the tumor core (classified as T cell–enriched)." (PMID 40561008, 2025). "Arguing for a direct effect, conditional ablation of Ptpn11/SHP2 in CD4 T cells increased tumor progression in a melanocyte model." (PMID 40992926, 2025). "Beyond their helper function, certain CD4+ T-cell subsets possess direct cytotoxic activity and perform important functions in controlling other immune cells and modifying the tumor microenvironment (TME) by secreting cytokines." (PMID 40860882, 2025). "These activated apCAFs then modulate the CD4+ /CD8+ T cell ratio to promote tumor immunosuppression." (PMID 41164803, 2025). "Resting memory CD4+ T cells are essential for regulating tumor dynamics and maintaining long-term immune memory through specific regulatory mechanisms." (PMID 39895793, 2025). "The observation that IL-12 increases the presence of OX40 on the surface of CD4 T cells initiated the study of a combined anti-tumor capacity." (PMID 40430543, 2025). "On the contrary, Trex1 knockdown in the tumor increased tumor infiltration of CD4+ T cells, CD8+ T cells, NK cells, and DCs, and decreased MDSCs." (PMID 41117130, 2025).